MR1 (major histocompatibility complex, class I-related)
Diseases named in the same sentence as MR1 in open-access papers (continued):
Sharing a sentence is not in itself a finding about the gene and the disease.
tumor (continued). "Importantly, such MAIT-cell-mediated anti-tumor activity is independent of MR1 expression on tumor cells, implying that tumor recognition by MAIT cells via cognate MR1–TCR interaction may not be required." (PMID 36551916, 2022). "To determine the molecular basis underlying the protective effects observed above, we isolated NK cells and MAIT cells from PBS- versus 5-OP-RU-treated B6-MAITcast MR1 WT mice with and without B16F10 tumor challenge and performed RNA-seq." (PMID 34362900, 2021). "The non-conventional MR1-dependent TCRs and NKG2D CAR T-cells are of high interest for universal tumor targeting." (PMID 33670139, 2021). "Interestingly, tumor targeting by MAIT cells in vivo seemed not to be completely dependent on MR1 expression on tumor cells, since MR1 knockout had only minor effect on MAIT cell antitumor response." (PMID 36463401, 2023). "In an experiment involving fibrosarcoma induced by MCA, long-term monitoring results showed that mr1−/− mice exhibited stronger resistance to MCA than wild-type mice, demonstrating that the lack of MAIT cells can provide better protection against tumor formation." (PMID 35733919, 2022). "Mucosal-associated invariant T (MAIT) cells, a type of unconventional T cells that rely on MHC class I-related protein 1 (MR1) for their development and function, have always been known for their antimicrobial properties; however, recent reports have revealed their negative role in tumor immunity." (PMID 35733919, 2022). "However, to the best of our knowledge, comprehensive functional studies on CAR-MAIT cells in suppressing tumor growth have not been reported, though we expect more functional studies related to CAR-MAIT cell therapy will soon appear due to recent advances of MR1 tetramers." (PMID 35565395, 2022). "We could not detect MR1 expression on OAC tumor cells, either in fresh collagenase-digested biopsies, or from trypsinised OE33 cell lines (data not shown), whereas Gherardin and colleagues demonstrate MR1 upregulation in a K562 cell line after pulsing with folate-derived antigens." (PMID 31354725, 2019).
cancer (61 papers, 2011 to 2025). A tumor composed of atypical neoplastic, often pleomorphic cells that invade other tissues. "This diverse MR1T clone exhibits pan-cancer cytotoxicity to kill various types of cancer cells, but not a pan-population effect in humans, due to its restriction by an unusual MR1 allomorph with an R9H mutation in humans." (PMID 40746558, 2025). "MR1 allotype testing of recognized cancer lines led the authors to concluded that MC.7.G5 TCR-expressing T cells exhibited on-target cancer-reactivity across several MR1 allelic variants." (PMID 39744940, 2025). "7G5.TCR-T and 7G5-like TCR-T cells reacted to both cancer and healthy cells endogenously expressing MR1*04 SNVs, which encode R9H and H17R substitutions." (PMID 39445059, 2024). "Healthy individuals harbor T cells reactive to MR1 variants displaying self-ligands expressed in cancer and benign tissues." (PMID 39445059, 2024). "Efforts to identify a biomarker for reactivity of 7G5.TCR-T led to the discovery that one rare (approximately 1:100) allele of MR1, MR1*04, predicted cancer cell line reactivity." (PMID 39445059, 2024). "MR1-restricted T cells have been implicated in microbial infections, sterile inflammation, wound healing and cancer." (PMID 38402309, 2024). "Expression of MR1 has been shown in a variety of human cancers, and certain MR1 mutations were found to disrupt MAIT cell activation in mice." (PMID 33919687, 2021). "MAIT cells are MR1-restricted T cells that are well-known for their anti-microbial properties, but they have recently been associated with different forms of cancer." (PMID 32508830, 2020). "Nevertheless, better understanding of the mechanism of action of MR1-restricted T cells and identification of cancer-associated ligands presented by MR1 is crucial for reaching this goal." (PMID 32183246, 2020). "Overexpression of MR-1 is associated with cancer cell proliferation and migration in human hepatoma HepG2 cells." (PMID 21702971, 2011). "Recognition of MR1*01/*04 A549 cells suggests the rare MR1*04 variant might be a more sensitive TCR ligand for the MC.7.G5 TCR than MR1*01 or MR1*02 or indicate that the MR1*04 protein might present the cancer ligand better than other MR1 variants." (PMID 39744940, 2025). "Collectively, these data highlight the need for a deeper understanding of MR1 biology in the context of cancer and raise the possibility that MR1 polymorphism may need to be considered in the context of allotransplantation and graft vs. host disease (GvHD)." (PMID 39445059, 2024). "We next explored the possibility that the preferential reactivity of 7G5.TCR-T to MR1*04 allele-expressing cancer cells might be due to MR1*04 being more abundantly expressed at the cell surface than MR1*01." (PMID 39445059, 2024). "Worth mentioning is the fact that, in several different cancers, including glioma, melanoma, colorectal, stomach, liver, pancreatic, head and neck, cervical, endometrial, and ovarian cancers, a high MR1 expression level is associated with decreased probability of survival." (PMID 32756356, 2020). "Also, overexpression of MR-1 can activate the nuclear factor κB signaling pathway, which is linked to a wide variety of diseases including cancer, inflammation and autoimmune disease." (PMID 21702971, 2011). "Major histocompatibility complex class I-related protein 1 (MR1) plays a central role in the immune recognition of infected cells and can mediate T cell detection of cancer." (PMID 40763744, 2025). "Both MC.7.G5 and MC.27.759S T cell clones expressed CD8-αβ, and CD8 expression in Jurkat cells expressing these and other MR1-restricted TCRs enhanced the response to cancer targets." (PMID 39744940, 2025). "Of the remaining cancer-activated MR1-restricted TCRs, some used the MAIT cell–preferred TRAJ20 and TRAJ12 to generate a similarly placed tyrosine and others used TRAJ26, TRAJ47, or TRAJ32 to encode this tyrosine residue." (PMID 39744940, 2025).
cancer (continued). "Macrophages express high levels of MR1, especially M2‐polarized macrophages and endogenous TAMs, in cancer patients, providing a foundation for the anti‐TAM response of MAIT cells." (PMID 41179703, 2025). "Here, we present an MS-based method to investigate MR1-bound antigens at the cell surface of cancer cells." (PMID 40763744, 2025). "Of the MR1-restricted cancer-reactive T cell lines that were generated, 3 of 6 expressed CD161, with levels residing between that of MC.7.G5 and MC.27.759S." (PMID 39744940, 2025). "We recently described an MR1-restricted T cell clone that responded to a wide range of cancer cell lines while remaining inert to healthy cells." (PMID 39744940, 2025). "We conclude that there are strong biases within the TCRs of T cell populations that respond to cancer cell targets through MR1." (PMID 39744940, 2025). "TCR sequencing of MR1-restricted cancer-activated T cells showed that the majority of these cells shared a conserved 10-amino acid–long TCR-α chain motif as a result of TRAJ42 use." (PMID 39744940, 2025). "Although our results with MC.7.G5 TCR-transduced CD8+ T cells show some preferential recognition of MR1*04+ cancer cells, we were unable to reproduce the large differences in recognition observed in a previous study." (PMID 39744940, 2025). "Recent developments suggest that the role of MR1 extends to presenting antigens from cancer cells, a function dependent on the K43 residue in the MR1 antigen binding cleft." (PMID 39744940, 2025). "It was noticeable that all TRAJ42-containing cancer-activated MR1-restricted TCRs maintained a similarly placed tyrosine residue." (PMID 39744940, 2025). "Specifically, these MR1-restricted self-reactive human T cells from blood samples of healthy donors or cancer patients mostly express diverse TCRs (diverse MR1T or TRAV1-2- MR1T)." (PMID 40746558, 2025). "These T cells were able to respond to WT levels of MR1 on a wide range of cancer cell lines from many different origins but remained inert to healthy CD14+ monocytes and B cells from multiple individuals." (PMID 39744940, 2025). "Other researchers have also described similar cancer-reactive MR1-restricted T cells that target non-MR1*04+ targets." (PMID 39744940, 2025). "Expression of MR1*01 as a single chain (sc) β2M-MR1 protein in the MR1-KO cancer cells restored killing by MC.27.759S." (PMID 39744940, 2025). "The limited allelic variation of MR1 compared to HLA makes it an attractive target for potential cancer therapies." (PMID 40362653, 2025). "Recent studies have shown that MR1 can present self antigens to MR1-restricted T cells with a single MR1-restricted T cell being able to kill a wide range of cancer cell lines and primary cancer cells while remaining inert to healthy cells." (PMID 39744940, 2025). "Sequencing of the MR1-restricted, cancer-reactive T cells from Donor 1 using a microfluidics-based single-cell sequencing platform revealed 3 paired TCRs, with 2 of the α chains being paired with 1 TRB chain." (PMID 39744940, 2025). "TRAJ42 was paired with 6 different TRAV genes within the cancer activated MR1-restricted T cell population." (PMID 39744940, 2025). "Next, we tested CD8+ T cells from Donor 216T expressing the MC.7.G5 TCR against a wider panel of MR1*01+/+ or MR1*01/*02 cancer cells." (PMID 39744940, 2025). "The remaining discussion point concerns why the rare MR1*04 variant appears to be a better ligand for the MC.7.G5 TCR and other cancer-activated MR1-restricted TCRs." (PMID 39744940, 2025). "The limited allelic variation of MR1 compared with HLA makes it an attractive target for potential cancer therapies." (PMID 39744940, 2025). "More diverse MR1T clones respond to cancer cells, dependent on the dominant MR1 allomorph in humans." (PMID 40746558, 2025).
cancer (continued). "In this context, the immune-dysregulated cancer microenvironment inherently impacts the availability and specificity of polar metabolites for MR1, which in turn critically influences MAIT cell activation downstream." (PMID 40746558, 2025). "A T-cell clone, MC.7.G5, has been described as MR1-restricted, exhibiting pan-cancer reactivity, and failing to recognize normal cells or cells subject to various forms of cellular stress." (PMID 39445059, 2024). "Jurkat cells expressing 7G5, the 7G5-like TCR 759S, or the MR1T TCR TC5A87 displayed a similar pattern of reactivity against cancer cell lines, exhibiting elevated reactivity to MR1*04 cells and limited reactivity to MR1*01 and MR1*02 lines." (PMID 39445059, 2024). "The promise of MR1-restricted TCR-based therapy for cancer has arisen through the discovery of T cells from human donors that appear to be restricted to MR1-ligand targets preferentially found in cancer." (PMID 39445059, 2024). "This study investigates and confirms that MR1 possesses the ability to recognise recognise T cell receptors (TCRs) in several types of cancer cells." (PMID 39427211, 2024). "Described “cancer-specific” MR1-restricted TCRs need further validation, covering conserved allomorphs of MR1." (PMID 39445059, 2024). "As MAIT cells encounter an ongoing barrage of signals - from cancer cell antigens presented by MR1 to inflammatory cytokines and chemokines - they initially respond robustly." (PMID 38545100, 2024). "Our findings reveal that cancer-reactive MR1-restricted T cells infiltrate tumors in an antigen-dependent manner." (PMID 39451228, 2024). "In this article, MR‐1 indirectly exerts its cancer promoting effect by maintaining the stability of NICD3 in the cytoplasm by inhibiting ITCH." (PMID 38342606, 2024). "We reasoned that if 7G5 binds to MR1*04 in a ligand-agnostic fashion, then saturating the surface MR1 of cancer lines expressing MR1*04 with the bacterial ligand acetyl-6-formylpterin (Ac-6-FP) should not block recognition." (PMID 39445059, 2024). "Recently, MR1-restricted T cells were discovered that were reactive to a group of human cancer cell lines." (PMID 39451228, 2024). "Such cells express markers of conventional MAIT cells and become activated in response to multiple ligands presented by MR1*01 overexpressed on cancer lines." (PMID 39445059, 2024). "The discovery of rare T-cell clones capable of recognizing potential “pan-cancer” MR1-restricted ligands has led to intense efforts to learn more about the biology of MR1 and MR1-restricted T cells in cancer." (PMID 39445059, 2024). "In cancer immunotherapy, inhibiting MHC class I-related protein 1 (MR-1) on cancer cells can be used to develop MAIT-cells-based treatments." (PMID 37508372, 2023). "Only in MS and cancer has human MR1 expression been investigated in terms of disease severity outcomes." (PMID 36944969, 2023). "A population of MR1-restricted T cells has been identified that respond to an unidentified cancer metabolite on cancer cells." (PMID 38567060, 2023). "MR1 is widely expressed in different cancer cells and varies little between individuals, which offers opportunities for pan-cancer immunotherapies that can simultaneously target diverse tumor types." (PMID 36483679, 2022). "The infiltration of MAIT cells was associated with cancer initiation and growth in an MHC class I-like molecule (MR1)-dependent way." (PMID 35578660, 2022). "This new group of T cells has been named MR1T and has been shown to recognize and eliminate a wide range of cancer cells that express MR1." (PMID 33506055, 2021). "Researchers from Cardiff University in partnership with Enara Bio Ltd. are working on a clinical implementation of this type of TCR-directed T-cell therapy against unconventional cancer targets, such as MR1-presented cancer ligands." (PMID 33670139, 2021).
cancer (continued). "This is supported by the identification of a MR1-restricted T cell clone capable of killing multiple types of cancer in a TCR-MR1 dependent manner." (PMID 33808058, 2021). "This TCR exhibits a pan-cancer cell recognition potential via the invariant monomorphic MHC class I-related protein MR1 molecule." (PMID 34650571, 2021). "MR1 expression and MAIT cell abundance were significantly positively correlated in four human cancers, and that high MAIT cell abundance was in turn associated with OS and progression-free survival with different directions of effect in different cancers." (PMID 33919687, 2021). "The cells can easily be detected in the blood of healthy individuals and were classified as a new cell population based on their capacity to recognize MR1 and on their ability to react to different types of cancer cells." (PMID 33185693, 2020). "Given the possibility to overcome the limitations of extensive HLA polymorphism by exploiting monomorphic MR1 molecules, priority should be given to understand the roles of MR1-restricted T cells in cancer." (PMID 32411144, 2020). "In this work, we review the subsets of MR1-restricted T cells, their antigen presentation and cancer biology, and their potential applications in cancer immunotherapy." (PMID 32756356, 2020). "Most of our knowledge on MR1-restricted T cells in cancer comes from studies on MAIT cells, which have been shown to have a dichotomous role in prognosis." (PMID 32756356, 2020). "A recent study suggests that such MR1-mediated presentation of the metabolome of cancer cells is utilized by specific T cells for ubiquitous cancer targeting." (PMID 32272797, 2020). "Less is known about MR1T cells except that they were found in the blood of each healthy individual studied and MR1T cell clones were activated by cancer cell lines in an MR1-dependant manner." (PMID 32411144, 2020). "We are beginning to appreciate the diversity of microbial and endogenous (including cancer) antigens presented by MR1 and the heterogenous populations of T cells which recognize them." (PMID 33013835, 2020). "This review will discuss current knowledge regarding the roles of MR1-restricted T cells in cancer and their possible introduction in cell therapy." (PMID 32411144, 2020). "In 2017, Lepore and co-authors identified in human blood a novel population of MR1-restricted T cells that recognise cancer cells via MR1 presentation." (PMID 32183246, 2020). "Harnessing the biology of CD1- and MR1-restricted cells is currently highly regarded to fight cancer." (PMID 30116242, 2018). "The cells can be classified as a new cell population based on their capacity to recognize MR1 and how they react with different types of cancer cells." (PMID 28518056, 2017). "The number of apoptotic cells increased and MR-1 mRNA and protein levels decreased with increasing doses of either paclitaxel or carboplatin, strongly indicating that these anti-cancer drugs exert their therapeutic effects by antagonizing the effects of MR-1." (PMID 21702971, 2011). "Knockdown of MR-1 expression inhibited cell adhesion and invasion, and treatment with anti-cancer drugs decreased its expression in cancer cells." (PMID 21702971, 2011). "Myofibrillogenesis regulator 1 (MR-1) is overexpressed in human cancer cells and plays an essential role in cancer cell growth." (PMID 21702971, 2011). "Overexpression or knockdown of MR-1 in cancer cells was used to assess its role in cell proliferation, adhesion, and invasion." (PMID 21702971, 2011). "Knockdown of MR-1 expression inhibits cell adhesion and invasion, and anti-cancer drugs decrease the expression levels of MR-1 in cancer cells." (PMID 21702971, 2011). "Our recent methodology for identifying novel, stabilized Schiff base–bound MR1 ligands at the cell surface via crosslinking mass spectrometry will hopefully aid the discovery of new, natural MR1 ligands, including those recognized by CAITs and other cancer-activated MR1-restricted T cells." (PMID 39744940, 2025).